GORAB (golgin, RAB6 interacting)
Description:
Plays a role in the organization and function of the Golgi apparatus. Involved in protein post-translational modification, particularly glycosylation of extracellular matrix proteins. Functions at the trans-Golgi by cooperating with SCYL1 to promote COPI coat assembly into discrete functional domains, supporting Golgi organization and trafficking.
Synonyms: NTKL-BP1; NTKLBP1; SCYL1BP1; FLJ11752; GO
Tractability: No criterion of Open Targets' tractability assessment is met for any kind of drug.
Gene: Protein-coding gene on chromosome 1 (170,531,819 to 170,553,834, forward strand). Ensembl gene ENSG00000120370.
Subcellular location: Cytoplasm; Golgi apparatus; Golgi apparatus, trans-Golgi network
Subcellular location (Human Protein Atlas): Golgi apparatus; Nucleoplasm; Cytosol; Nucleoli
Gene Ontology:
Molecular function: protein binding; protein-macromolecule adaptor activity
Biological process: protein N-linked glycosylation; non-motile cilium assembly
Cellular component: cytoplasm; Golgi apparatus; trans-Golgi network
Genetic constraint (gnomAD): Loss-of-function variants: 16 observed, 30.29 expected, observed/expected ratio (o/e) 0.53, 90% interval 0.36 to 0.8. The upper end of that interval is the gene's LOEUF score, 0.8, which puts it in group 3 of 6, group 1 being the genes least tolerant of losing a copy. Missense variants: 439 observed, 456.53 expected, observed/expected ratio (o/e) 0.96, 90% interval 0.89 to 1.04. Synonymous variants: 180 observed, 166.13 expected, observed/expected ratio (o/e) 1.08, 90% interval 0.96 to 1.23.
Gene-disease validity (ClinGen):
ClinGen rates the evidence that GORAB causes each of these diseases.
geroderma osteodysplastica (autosomal recessive): Definitive.
Homologues: Orthologues: chimpanzee GORAB (99% identical), macaque GORAB (95% identical), rabbit GORAB (85% identical), pig GORAB (82% identical), dog GORAB (80% identical), guinea pig GORAB (76% identical), mouse Gorab (75% identical), rat Gorab (75% identical), tropical clawed frog gorab (51% identical), zebrafish gorab (40% identical), Drosophila melanogaster Gorab (21% identical).
Diseases named in the same sentence as GORAB in open-access papers:
GORAB is named in the same sentence as 13 diseases in open-access papers, as found by Europe PMC text mining. Sharing a sentence is not in itself a finding about the gene and the disease. The quoted sentences say what the papers report.
gerodermia osteodysplastica (8 papers, 2017 to 2024). "Loss‐of‐function mutations of the gene GORAB in gerodermia osteodysplastica (GO) cause shortening of glycan chains in proteoglycans such as the small leucine rich proteoglycans (SLRPs)." (PMID 39234801, 2024). "GORAB encodes a Rab6-interacting Golgi protein, and its mutations cause human genetic disorder, gerodermia osteodysplastica, which is characterized by skin laxity and early-onset osteoporosis." (PMID 34901009, 2021). "GORAB loss-of-function mutations have been linked to Gerodermia osteodysplastica GO, OMIM 231070;, an autosomal recessive inherited disorder characterized by lax and wrinkly skin, which gives patients a prematurely aged appearance." (PMID 33321764, 2020). "Moreover, findings obtained from human studies showed that autosomal recessive mutations of GORAB cause gerodermia osteodysplastica, which is characterized by wrinkly skin and osteoporosis." (PMID 29281706, 2017).
osteoporosis (2 papers, 2017 to 2024). A condition of reduced bone mass, with decreased cortical thickness and a decrease in the number and size of the trabeculae of cancellous bone (but normal chemical composition), resulting in increased fracture incidence. "Loss of GORAB function in gerodermia osteodysplastica (GO) causes shortening of glycosaminoglycan chains, leading to extracellular matrix disorganization that results in wrinkled skin, osteoporosis and elevated TGF‐β signaling." (PMID 39234801, 2024).
Autosomic Recessive Cutis Laxa type 2 (1 paper, 2019). "GORAB compound heterozygous variants and the clinical features of patient P5 were compatible with Geroderma osteodyplastica (GO) or Autosomic Recessive Cutis Laxa type 2 (ARCL2) diagnoses." (PMID 31829210, 2019).
connective tissue disorder (1 paper, 2023). A disease involving the connective tissue. "In human patients, mutations in ATP6V0A2 and GORAB cause overlapping connective tissue disorders, which is reflected in the misregulation of the mesenchymal trajectory of Atp6v0a2 and Gorab mutants." (PMID 37968388, 2023).
GORAB also shares sentences with these, for which no sentence is quoted: bovine tuberculosis (1 paper); Costello syndrome (1); cutis laxa (1); diabetes (1); hepatocellular carcinoma (1); Macrocephaly (1); neuromuscular disease (1); progeroid syndrome (1); tumor (1).